HIF1A (hypoxia inducible factor 1 subunit alpha)
Diseases named in the same sentence as HIF1A in open-access papers (continued):
Sharing a sentence is not in itself a finding about the gene and the disease.
tumor (continued). "Together suggest IRISOE enhances production/secretion of IL-1β in TNBC tumor cells under normal/normoxic, as well as hypoxic (e.g., within the aggressiveness niche in IRISOE TNBC tumors) conditions through stabilization of HIF-1α and/or activation of AKT, ERK and/or NF-κB signaling." (PMID 29262555, 2017). "Because CXCL12 is the target molecule of HIF-1α, the hypoxic condition resulting from bevacizumab treatment could lead the tumor cells to produce CXCL12, which would in turn prompt the CXCR4+ cells to migrate into the tumor." (PMID 29286323, 2017). "Importantly, depletion of HIF-1α KO NK cells rescued tumour growth without inducing changes in sVEGFR1 and vascular morphology." (PMID 29150606, 2017). "After treatment the tumour partial oxygen pressure was measured by LiPc electron paramagnetic resonance oximetry and the expression of epidermal growth factor receptor (EGFR), phosphorylated EGFR, Ki-67, MCT1, MCT4, GLUT1, CAIX and HIF-1α were investigated by immunohistochemistry." (PMID 28756482, 2017). "Furthermore, BA/CDM combination additively increases ROS generation with subsequent DNA damage and apoptosis, and significantly suppresses the HIF1α pathway with decreased VEGF expression, subsequently suppressing AML tumor growth from both the in vitro and in vivo mice model." (PMID 29212263, 2017). "Bellot and colleagues reported that the HIF-1α target genes, BNIP3 and BNIP3L, are responsible for the induction of autophagy under hypoxic conditions via disruption of the Bcl-2:Beclin1 complex, and HIF-mediated autophagy is a survival mechanism involved in tumor progression." (PMID 28841148, 2017). "To test whether the suppression of HIF-1α can be explored as a treatment strategy for PEL, we utilized PX-478, a small molecule that has been shown to potently inhibit the expression of HIF-1α in a variety of tumor models and mice." (PMID 28922425, 2017). "It is notable that memory Tc1 cells were relatively unaffected by inhibition of HIF-1α, suggesting that anti-neoplastic drugs such as Echinomycin might be used without affecting some tumor-specific memory CD8+ cell functions." (PMID 28542595, 2017). "Taken together, these data suggest that LncHIFCAR augments the transcriptional activity of HIF-1α and serves as a critical regulator of HIF-1 transcriptional network, which enhances the anchorage-independent growth and provides a growth advantage for tumour cells for hypoxia adaptation." (PMID 28639619, 2017). "Metabolic reprogramming is crucial for tumor progression to foster cancer cells growth and proliferation, and is regulated by mechanistic target of rapamycin (mTOR) and AMP-activated protein kinase (AMPK) as well as the oncogenes Myc and hypoxia inducible factor 1α (HIF-1α)." (PMID 28574837, 2017). "A recent study showed that reduction of LDH-A, a direct target gene of HIF-1α, decreased cellular transformation and significantly increased apoptosis, as well as delayed tumor development and metastases, indicating that LDH-A is involved in tumor initiation and progression." (PMID 28790395, 2017). "On the other hand, a lack of oxygen due to the rapidly growing tumor mass cause the inactivation of prolyl hydroxylase (PHD) preventing VHL from recognizing and binding to HIF-1α and thus leading to HIF-1α accumulation, which induces the transcription of genes involved in adaptation to hypoxia." (PMID 29050245, 2017). "The reason might be tumor tissues with HIF-1α protein high expression appeared tissue necrosis, which resulted in a huge amount of HIF-1α entering the bloodstream, or there was a special regulation mechanism in hematological system itself of patients with NSCLC." (PMID 26853843, 2016). "Interestingly, the mechanisms of EMT, Hif1-α signalling and DNA damage repair were all reported to be regulated by phosphorylation of upstream proteins, such as Erk, AKT and STAT339, 40, 41, 42, 43, which were reported to promote drug resistance in tumours." (PMID 27011063, 2016).
tumor (continued). "Speculatively, activation of HIF-1α could be critical for DTC to survive in these bone marrow niches or, alternatively, oxygen-independent upregulation of HIF-1α could arise from upregulation of upstream signaling pathways involved in tumor progression." (PMID 27105499, 2016). "On the other hand, it has been shown that decreased HIF-1α expression, due to up-regulation of a basic helix-loop-helix (bHLH) transcriptional repressor (SHARP1, bHLHE41 or DEC2), may inhibit tumor growth and angiogenesis via a negative regulation of VEGF expression." (PMID 27126599, 2016). "Deletion of Hif-1α but not Hif-2α in macrophages diminished tumor outgrowth in the MCA-model." (PMID 27015123, 2016). "Western blot with VEGF antibody and IHC with an antibody against CD31, a vascular marker, showed that overexpression of DEK promoted VEGF expression and tumor angiogenesis, and HIF-1α knockdown inhibited but not abolished DEK-mediated enhancement of VEGF expression and angiogenesis." (PMID 26988756, 2016). "Pharmacological inhibition of HIF-1α has been tried in a multitude of cancers with limited success, most likely due to the complexity of the HIF-1α transcriptome, which contains not only genes that promote tumor cell survival but also genes that promote growth arrest and tumor cell death." (PMID 27764809, 2016). "Indeed, accumulation of ROS in Vdac1−/− RAS MEF-derived tumors triggered HIF-1α stabilization, abnormal vasculature, and leakage of red blood cells, thus generating an inflammatory response that resulted on a strong impact on VDAC1 tumor development." (PMID 27625993, 2016). "Moreover, recent data from syngeneic murine tumour models of Lewis lung carcinoma (LLC) and B16-F1 (B16) melanoma cancer cell lines showed that lactate-induced stabilisation of HIF-1α increased arginase 1 expression and consequently M2-like polarisation of tumour-associated macrophages." (PMID 26099350, 2016). "HIF-1α knockdown reduced but not abolished the ability of DEK to promote MDA-MB-231 tumor growth." (PMID 26988756, 2016). "To test this idea, we analyzed the expression levels of HIF1α and OATP1B3, a representative member of OATP family, in PDX-derived tumor tissues, and found high expression of both proteins, with HIF1α and OATP1B3 expressed in the nucleus and cytoplasm of tumor cells respectively in all 3 PDX samples." (PMID 27329598, 2016). "Additionally, HIF-1α could mediate the expression of VEGF, an important factor that promotes angiogenesis and is involved in tumor angiogenesis." (PMID 26958938, 2016). "However HIF-1α and HIF-2α have contrasting effects on experimental tumor progression." (PMID 26262842, 2015). "Furthermore, HIF1α(PP)-induced U-87 MG cells showed ~10-fold increase in the development of tumor spheres but no increase in anchorage-independent growth." (PMID 25893706, 2015). "Finally, we show that the small-molecule ILK inhibitor T315 can disrupt this regulatory loop in vivo and suppress xenograft tumor growth, thereby providing proof-of-concept that targeting ILK represents an effective strategy to block HIF-1α expression and aggressive phenotype in cancer cells." (PMID 25821081, 2015). "Finally, regulators focused on upstream pathways of HIF-1α and glycolysis, especially PI3K and AMPK pathways, could also be a source of tumor metabolic inhibitor or energy restriction mimetic agents (ERMAs)." (PMID 25685782, 2015). "However despite homology between HIF-1α and HIF-2α there are evidences that in VHL-defective renal cell carcinoma HIF isoforms exhibit different or opposite effect on gene expression and proliferation of tumour cells." (PMID 26146622, 2015). "With respect to U-118 MG, 8-week intermittent induction of HIF1α(PP) failed to result in discernible morphological differences in culture but apparently helped tumor maintenance, as indicated by the preserved bioluminescent signals throughout a 7-week period of observation." (PMID 25893706, 2015).
tumor (continued). "We could not find any other reports on the effect of A2P on HIF-1α levels, but several studies show that A2P inhibits tumor invasion, while it also inhibits melanogenesis in melanocytes." (PMID 26547841, 2015). "Because CXCL12 is the target molecule of HIF-1α, the hypoxic condition resulting from bevacizumab treatment could lead the tumour cells to produce CXCL12, which would in turn prompt the CXCR4+ cells to migrate into the tumour." (PMID 26635184, 2015). "Thus, it has recently been proposed for certain syngeneic transplantable solid murine tumors that lactate production by the tumor cells generates a conserved, “alternative activation-like” TAM signature that is orchestrated by HIF-1α and characterized by arginase-1 and VEGF activation." (PMID 25702581, 2015). "Furthermore, HIF-2α but not HIF-1α, can over-ride the tumor suppressor activity of pVHL in experimental tumor systems." (PMID 26262842, 2015). "However, the expression levels of HIF-1α were not significantly correlated with either tumor differentiation or staging status." (PMID 26018028, 2015). "One possible mechanism links HIF-1α to an increased expression of metalloproteinase ADAM10 leading to a decrease in surface MHC class I chain-related molecule A (MICA) levels, which in turn leads to tumour cell resistance to lysis mediated by innate immune effectors." (PMID 26435741, 2015). "Previous studies have found overexpression of HIF-1α in various human cancers may play an important role for cancer progression, which implied that HIF-1α is an essential transcriptional regulator of tumor microenvironment." (PMID 25816356, 2015). "However, expressions of angiogenesis-related genes such as HIF1α, VEGF and tumor invasion-related genes like MMP2, MMP9, E-cadherin and β-catenin were increased by either carbon ion beam or X-ray irradiation alone and/or in combination with gemcitabine compared to." (PMID 25849939, 2015). "In RCC, HIF-2α, but not HIF-1α, promotes tumor growth in xenograft models." (PMID 25590810, 2015). "Our results did reveal that the protein as well as the mRNA expression for HIF-1α were the lowest in this subgroup even when corrected for tumor grade (data not shown), as reported in the literature, but the difference from TNBC failed to meet statistical significance." (PMID 26046764, 2015). "HIF-1α signaling in response to hypoxia has been described as important for myeloid cell function in the TME, but although tumor hypoxia and HIF-1α regulate MDSC differentiation, hypoxia does not seem to be the major driver of TAM differentiation into pro-angiogenic M2 subsets." (PMID 26673090, 2015). "We consider one reason for the smaller degree of HIF-1α enhancement observed in this study to be that the number of molecules having an effect on the HIF-1α expression in vivo is fewer than that seen in vitro, thus reducing the rate of enhancement of the Luc expression in the tumor xenograft model." (PMID 26034980, 2015). "Interestingly, during a ~5-week monitoring of tumor growth using bioluminescent imaging, we found that the increase in tumor volume from the β-gal-induced cells was equivalent to, if not greater than, that from the HIF1α(PP)-induced cells." (PMID 25893706, 2015). "Thus, although many details remain to be defined, our current understanding of the connections between ROS, HIF1α, VEGF and Survivin point towards the latter is a key point of convergence and a crucial component in determining tumor growth, progression, metastasis and drug resistance." (PMID 26584646, 2015). "Similarly in tumor cells, tanshinone-1 does not alter the mRNA levels of HIF-1α in tumor cells whereas the proteosome inhibitor MG-132 prevents the reduction of HIF-1α accumulation induced by tanshinone-1." (PMID 26202747, 2015).
tumor (continued). "This reduction in the tumor growth by 2-DG could be, in part, due to reduced insulin levels leading to attenuation of the insulin/IGF-1/PI3K/Akt/HIF-1α signaling pathway thereby possibly modulating the various cell cycle regulatory proteins (cyclin D, A, E) involved in the proliferation." (PMID 26135741, 2015). "However, this inhibitory effect of tumor hypoxia was blocked by PrPc knockdown independent of HIF-1α expression." (PMID 25742790, 2015). "While the sample size was limited and few patients received paired biopsies, decreases in HIF-1α expression were observed in four or the five patients with paired biopsies, including two patients who experienced a decrease in tumor size (although not reaching PR)." (PMID 25373733, 2014). "HIF-1α has a central role in regulating tumor behavior, including proliferation, apoptosis and migration, thus the inhibition of the HIF-1α pathway may be a promising strategy for attenuating tumor progression." (PMID 25120692, 2014). "Therefore, we hypothesized that RBP2 regulates HIF-1α through the activation of Akt signaling, and we further sought to detect the signaling mechanisms involved in RBP2-mediated tumor angiogenesis." (PMID 25162518, 2014). "That both VEGF and BNIP3, but not HIF-1α, protein levels were inversely correlated to the tumor ascorbate content agrees with the observation that FIH may be more dependent on ascorbate for activity than the PHDs." (PMID 24551593, 2014). "However, recent studies reported that HIF-1α and HIF-2α may play opposing roles in tumor angiogenesis." (PMID 24634660, 2014). "However, clinical utility of serum Ang-2 and MMP-2 and tumor HIF-1α was not addressed at this time and would need to be further evaluated and demonstrated." (PMID 25100134, 2014). "In another study in glycolytic glioma tumor cells in vitro, lactate exposure increased HIF-1α levels independent of hypoxia; in a similar study in vivo (mice), intraperitoneal lactate administration enhanced xenografted tumor growth, metastasis, and vascularity." (PMID 25988127, 2014). "Furthermore, knockdown of HIF-1α expression by adenovirus-mediated small hairpin RNA (shRNA) inhibits the angiogenesis and invasion in HCC cells and as a result, the levels of VEGF and MMP-2 are also repressed in endothelial cells transferred to the tumor." (PMID 25101278, 2014). "In addition, at moderate concentrations, 2-MeOE2 has no direct toxic effects on slowly dividing non-tumor cells; however, it does lead to reliable inhibition of HIF-1α." (PMID 25238237, 2014). "Suppressing HIF-1α expression using either shRNA or pharmacological blockade has negative effects on tumor growth and invasion, suggesting that targeting the hypoxic response may be clinically beneficial." (PMID 25166211, 2014). "The presence of proline-hydroxylated HIF-1α may also explain why there is a lack of correlation in tumours between HIF-1α levels and pO2 levels." (PMID 24563687, 2014). "While both cells lines expressed HIF2α, only UNC-R1 expressed HIF1α, suggesting that UNC-R2 cells have lost HIF1α expression as is seen in a proportion of ccRCC cell lines and primary tumors and consistent with the notion that HIF1α is potentially a tumor suppressor gene." (PMID 25180793, 2014). "In the other 21%, tumours had HIF-1α yet no detectable hydroxylated HIF-1α." (PMID 24563687, 2014). "Deficiency of HIF-1α can lead to non-healing chronic wounds whereas overexpression of HIF-1α can improve wound healing but could also induce hypertrophic scars and tumor growth." (PMID 25365172, 2014). "Moreover, inhibition of neovascularization by suppression of the HIF-1α/VEGF signaling pathway may delay tumor progression and perhaps even starve tumor cells to death." (PMID 24918449, 2014).
tumor (continued). "However, previous publications have demonstrated that hypoxic tumor cells stabilize the hypoxia-inducing factor-1α (HIF-1α) leading to the HIF-1α-dependent cell protection, increased transcription of vascular endothelial factor (VEGF), and tumor vessel formation." (PMID 24904829, 2014). "Under low oxygen conditions, both tumor cells and macrophages establish a proangiogenic program mediated by HIF-1, which is a transcriptional activator complex constituted with two types of subunits, an inducible α subunit (HIF-1α, HIF-2α, or HIF-3α), and the constitutively expressed HIF-1β subunit." (PMID 24829560, 2014). "Interestingly, the pleckstrin homology domain interacting with these proteins promoted degradation of HIF-1α independent of oxygen concentration and suppressed tumor progression." (PMID 25361009, 2014). "Moreover, miR-338-3p down-regulated tumor HIF-1α expression in mice treated with or without sorafenib." (PMID 25531114, 2014). "Furthermore, IMQ synergized with the glucose analog 2-DG and the 17-AAG which destabilizes the HIF-1α protein to induce apoptosis in tumor cells but not in primary human keratinocytes." (PMID 24658058, 2014). "However, the low blood supplies toward the tumour mass drives the tumour tissue into hypoxia, which may induce transcriptional activation of VEGF expression through HIF-1α stabilization." (PMID 24330494, 2013). "However, one HIF1A TG mouse showed proliferation of CD3-positive T lymphocytes (CD-4 positive cells predominated), with a monoclonal pattern of gene rearrangement in TCR, suggesting that the tumor cells were of monoclonal origin from alpha/beta type T cells." (PMID 23593116, 2013). "Interestingly, in murine models, deleting HIF1a in macrophages was shown to improve T cell function and tumor control, though surprisingly HIF1a deletion had this effect without influencing the vascularity of the tumor." (PMID 23653658, 2013). "In reduced oxygen conditions, HIF-1α binds to hypoxia-responsive elements which, in turn, stimulate the transcriptional coactivators CREB-binding protein and induces transcription of various target genes involved in tumor invasion, cell survival, and angiogenesis." (PMID 23731702, 2013). "Furthermore, NAC treatment did not change the protein abundance of Hif-1α in EO771 tumor lysates compared to controls as detected by Western blot." (PMID 23840457, 2013). "Their authors suggested that in such tumours VEGF expression may exhibit no pronounced dependence on expression of HIF-1α." (PMID 24153191, 2013). "Moreover, HIF-1α was found to localise in the cytosol of mouse tumour cells and did not accumulate in the nucleus." (PMID 23818933, 2013). "Moreover, miR-519c binds to the HIF-1α 3′UTR and thereby reduces tumor angiogenesis." (PMID 23802096, 2013). "Diffuse HIF-1α expression based on tumor types and its nonhypoxic activation through various genetic alterations that might result in different outcomes may also explain our observation." (PMID 24165149, 2013). "HIF1α expression was independent of Gleason score, tumor stage or type of treatment received." (PMID 23342109, 2013). "It should be added that only in the group of G3 adenocarcinomas over 50% of the tumours manifested high expression of the protein (+++) while no such strong HIF-1α expression could be noted in G1 or G2 tumours." (PMID 24153191, 2013). "However, even though the activation of HIF-1α may be a reasonable explanation, HIF-1α has been shown to be expressed in tumor cells even in the presence of oxygen (pseudo-hypoxia), and therefore, this piece of the puzzle remains unsolved." (PMID 23316163, 2012). "Tumor hypoxia was probed over a prolonged observation period in response to treatment with different cytotoxic agents, using a non-invasive bioluminescent ODD-Luc reporter system, in which part of the oxygen-dependent degradation (ODD) domain of HIF-1α is fused to luciferase." (PMID 23251549, 2012).